CD44 (CD44 molecule (IN blood group))
Diseases named in the same sentence as CD44 in open-access papers (continued):
Sharing a sentence is not in itself a finding about the gene and the disease.
renal fibrosis (continued). "We identified two CD8+ T cell subsets in a mouse model of UUO-induced renal fibrosis, Tc1 (CD44+CD25−CD62L−) and Tc2 (CD44+CD25highCD62Llow), which exert diverse effects in building an inflammatory and profibrotic environment." (PMID 34356613, 2021). "Our data clarify the mechanisms of pressure-induced EMT, establishing a rationale for developing miR-328 and CD44 as therapeutic targets for pressure-induced renal fibrosis." (PMID 24919189, 2014). "Our results suggest that miR-328-mediated CD44 transient upregulation is an important trigger of the pressure-induced EMT in renal fibrosis." (PMID 24919189, 2014). "The role of CD44 has rarely been investigated in Alport renal disease, although elevated levels of CD44 have been observed across several different kidney diseases, all of which are linked to fibrotic pathology, suggesting a pivotal role of CD44 in renal fibrosis." (PMID 40075271, 2025). "Nonetheless, the role of HA/CD44 in XLAS-related renal fibrosis is unexplored." (PMID 40075271, 2025). "To discern the role of CD44 in renal fibrosis, we constructed global CD44 knockout mice (CD44−/−)." (PMID 35312232, 2022). "Despite the previous implication of CD44 and RHAMM in renal fibrosis and disease, this study for the first time provides integral evidence for an important role of HA and both of its receptors in ORKP." (PMID 41301516, 2025). "Q-PCR indicated a significant reduction in the expression of renal fibrosis-related genes (fn-1, αSMA, Col1a1, Col3a1, Ctgf, fsp1, KIM) and inflammatory cytokines (Tgfα, Tgfβ, Il-1b, Il-4, Il-6, CD44, CD68) in the kidney of the acetate-treatment group." (PMID 36922584, 2023). "One such study showed that increased CD44 is expressed in the injured kidneys of normal mice, and CD44 KO mice subjected to UUO showed increased tubular injury and apoptosis but decreased renal fibrosis." (PMID 34009465, 2022). "To further identify the role of CD44 in renal fibrosis, we performed RNA sequencing in UIRI‐affected wild‐type mice and CD44 knockout mice." (PMID 35312232, 2022). "Following renal fibrosis, the infiltrated CD8 T cells were mainly Tc1 (CD44+CD25−CD62L−) at the early inflammation stage." (PMID 32921633, 2020). "Following renal fibrosis, the phenotypes of infiltrated CD8 T cells were mainly Tc1 (CD44+CD25−CD62L−) at the early inflammation stage and then changed to Tc2 (CD44+CD25highCD62Llow)." (PMID 32921633, 2020). "Here, we presented the first data showing that the transient downregulation of miR-328 by pressure could increase CD44 to induce renal tubular cell EMT, a major contributor to the pathogenesis of renal fibrosis, in tubular epithelial cells." (PMID 24919189, 2014). "The novel contribution of our study is finding that COL4A5 deficiency may lead to HAS2 overexpression and HA accumulation to activate CD44-TGFβ signaling, thereby promoting fibrosis, possibly suggesting that HAS2 and CD44 are potential therapeutic targets for impeding renal fibrosis in XLAS." (PMID 40075271, 2025). "In our study, M-MDSC supernatant and IL-15 regulated CD44 expression on the cell membrane of TGF-β1-induced MSCs, which suggested that M-MDSC supernatant and IL-15 may be involved in reducing the adhesion and migration of MSCs during renal fibrosis." (PMID 35252184, 2022). "Moreover, CD44 mRNA expression shows a negative correlation with the GFR in DKD patients, and increased levels are evident in renal fibrosis tissue and urine, alongside elevated complement components in DKD." (PMID 39050866, 2024).
cholangiocarcinoma (18 papers, 2014 to 2025). A carcinoma that arises from the intrahepatic biliary tree (intrahepatic cholangiocarcinoma) or from the junction, or adjacent to the junction, of the right and left hepatic ducts (hilar cholangiocarcinoma). "In this study, we investigated the prognostic significance of CD44 standard and variant isoforms in a cohort of 61 cholangiocarcinoma patients." (PMID 41514534, 2025). "However, our recent publications demonstrated that DNA lesions (8-oxodG and 8-nitroguanine) were formed in CSCs that had Oct3/4 expression in S. haematobium-associated bladder cancer, and CD133, Oct3/4, oval marker 6 (OV6) and CD44 expressions in O. viverrini-associated cholangiocarcinoma." (PMID 25547488, 2014). "Cholangiocarcinoma Cluster of differentiation 44 (CD44) is a family of transmembrane glycoproteins containing extracellular transmembrane and intracellular cytoplasmic domains." (PMID 33780455, 2021). "In cholangiocarcinoma (CCA) lnc-PKD2–2-3 increased CD44, CD133 and OCT4 expression as well as the CD44 + CD133+ cell proportion, raised tumor sphere forming efficiency and enhanced tharapy resistance to 5-FU in TFK-1 and Huh-28 cells." (PMID 33588867, 2021). "This study examined the role of CD44 on the progression of Cholangiocarcinoma (CCA) using metabolic profiling to investigate the molecular mechanisms involved in the Akt signaling pathway." (PMID 33780455, 2021). "The prognostic value of the complete loss of the CD44 expression program—simultaneously negative for standard (s), v5, and v6 isoforms—has not been characterized in cholangiocarcinoma." (PMID 41514534, 2025). "In this study, the enhanced interaction between MIF and CD74 + CD44 in cholangiocarcinoma may inhibit tumor apoptosis and promote angiogenesis by activating the downstream PI3K/Akt signaling pathway." (PMID 38702814, 2024). "Similarly in cholangiocarcinoma, the positive expression of CD44 was significantly related to large tumour size, high histologic grade, lymph node metastasis and distant metastasis." (PMID 34944493, 2021). "Moreover, CD44 silencing by siRNA suppressed aggressiveness, migration, and adhesion in cholangiocarcinoma cell lines." (PMID 31450710, 2019). "CD133, Oct3/4, CD44 and oval marker 6 (OV6) were proposed to be stemness markers in liver fluke-related cholangiocarcinoma." (PMID 25547488, 2014). "In conclusion, this preliminary study demonstrates that while individual CD44 isoforms are not independent prognostic markers in cholangiocarcinoma, the complete absence of CD44s, v5, and v6 expression characterizes a potential “CD44s-v5-v6 Null” subtype." (PMID 41514534, 2025). "Here we also found that glucose depletion in cholangiocarcinoma organoids induced an increase in their expression of stem cell markers, including LGR5, CD44, EpCAM, NANOG and OCT4 and more pronounced stem cell phenotypic characteristics such as resistance to gemcitabine." (PMID 31835877, 2019). "Furthermore, correlation analysis using cholangiocarcinoma datasets from The Cancer Genome Atlas (TCGA-CHOL) showed that WNT pathway genes (AXIN2, CTNNB1, LEF1) positively correlated with TIC signature genes (KIT, SALL4, CD44, SOX2)." (PMID 39774471, 2025). "We selected 5 markers: CD44 and GPC4 were enriched in EVs from PDAC and cholangiocarcinoma organoids, while VGLUT2, CD14, and annexin A11 were enriched in EVs from PDAC organoids but not cholangiocarcinoma organoids." (PMID 32990680, 2020).
chronic lymphocytic leukemia (18 papers, 2014 to 2025). "Moreover, RG7356 induced rapid internalisation of CD44 in chronic lymphocytic leukaemia cells expressing the zeta-associated protein of 70 kDa (ZAP-70), resulting in ZAP-70 inhibition and subsequently promoting caspase-dependent apoptosis." (PMID 34944493, 2021). "In chronic lymphocytic leukaemia (CLL) CD44 is part of a surface molecular complex together with ⍺4β1, CD38, CXCR4, and MMP‐9 that is absent in normal B‐cells and coordinates adhesion and homing of CLL cells." (PMID 40690545, 2025). "In patients with B-cell chronic lymphocytic leukemia, the median CD44 level in serum was 450 ng/mL86." (PMID 34599251, 2021). "The P6 peptide, FDAIAEIGNQLYLFKDGKYW, is a novel CD44-binding peptide that was identified from studying the interaction of pro matrix metalloproteinase-9 (pro-MMP-9) with CD44 as it relates to the proliferation of chronic lymphocytic leukemia (CLL) cells." (PMID 31877739, 2019). "CD-44 is involved in apoptotic response and promotion of disease development in chronic lymphocytic leukemia." (PMID 29416786, 2018). "In chronic lymphocytic leukemia cells exhibiting high levels of cell surface CD44, the engagement of CD44 by HA activated the PI3K/Akt and MAPK pathways to induce the expression of anti-apoptotic proteins and, in turn, promote survival." (PMID 26322272, 2015). "CD44 seems to be involved in the survival signaling of chronic lymphocytic leukemia, too." (PMID 32517153, 2020). "Genetic loss of CD44 in murine chronic lymphocytic leukemia had a negative impact on the phosphoactivation of important antiapoptotic regulators, ERK1/2 and AKT kinases." (PMID 25823654, 2015). "Moreover, the CD44 monoclonal antibody has been demonstrated to be effective in chronic lymphocytic leukemia." (PMID 25886575, 2015). "CS is a ligand for CD44 and it protects chronic lymphocytic leukemia (CLL) cells from apoptosis." (PMID 29747682, 2018). "In chronic lymphocytic leukaemia (CLL) cells, CD44, integrin α4 (also known as CD49d) and pro-MMP-9 are physically linked to CD38 in a supramolecular cell surface complex." (PMID 24713998, 2014). "In addition, a humanized mAb specific for CD44 (RG7356) was found to be cytotoxic to leukemia B cells without affecting the viability of normal B cells in chronic lymphocytic leukemia cells." (PMID 29747682, 2018).
colon adenocarcinoma (18 papers, 2010 to 2024). "The purpose of the current study is to assess the expression of MACC1, CD44, Twist1, and KiSS-1 in the colonic adenocarcinoma (CAC) tissues of patients and their associations between pathological characteristics and prognosis of patients with CAC." (PMID 30021598, 2018). "To determine whether SETD5 plays a role in CSC function, we investigated the association between SETD5 and the CSC markers CD133 and CD44 in colon adenocarcinoma." (PMID 37963940, 2023). "However, the associations of MACC1, CD44, Twist1, and KiSS-1 in colonic adenocarcinoma (CAC) invasion and metastasis remain unclear." (PMID 30021598, 2018). "The significant association found in our study between Reg4, CD44, and CD44ICD gives biological credibility to this pathway within a clinical cohort of colon adenocarcinoma patients." (PMID 33659040, 2021). "Oncomine analysis of cancer vs. normal tissue showed that CD44 mRNA was significantly higher in colon adenocarcinoma, colon mucinous adenocarcinoma, diffuse gastric adenocarcinoma, gastric intestinal type adenocarcinoma, gastric mixed adenocarcinoma." (PMID 27323782, 2016). "However, while CD44 tv4 (CD44s) expression is significantly lower in CRC than primary normal colon tissues (p≤0.001), CD44 tv3 (CD44v8-10) shows the opposite with enhanced expression in the colon adenocarcinomas samples." (PMID 32685007, 2020). "Studies showed that overexpression of MACC1, CD44, Twist1, and LNM and TNM stages were independent predictors of prognosis in patients with colonic adenocarcinoma." (PMID 39695175, 2024). "There were differential expressions of 62 miRNAs noted on the analysis of miRNA profiles of CSCs (CD133+/CD44+) and non-stem cells (CD13−/CD44−) from colon adenocarcinoma (SW116)." (PMID 32503256, 2020).
metastatic carcinoma (18 papers, 2009 to 2025). A carcinoma which has spread from the original site of growth to another anatomic site. "This new knowledge could provide the groundwork necessary for establishing new tumor markers and developing important, novel drugs targeted against HA/CD44-associated tumor progression, which can be utilized in the therapeutic treatment of metastatic cancer patients." (PMID 27070574, 2016). "The epithelial-to-mesenchymal transition marker that is highly expressed in primary and metastatic cancers, CD44, was significantly upregulated where a fibroblast stroma was present compared to a bone stroma (∼2-fold) (p < 0.0005)." (PMID 38226014, 2024). "The application of HA as a coating agent offers potential advantages, such as specific binding to cancer cells that overexpress CD44 and digestion by HAdase, found in various metastatic cancers." (PMID 35910012, 2022). "Although metastatic cancer cell exosomal CD44 has been shown to promote migration and invasion of poorly metastatic cancer cells, the underlying regulatory mechanism is still elusive." (PMID 35359362, 2022). "CD57 is typically related to luminal epithelial cells and primary non-metastatic carcinoma, while CD44 is a basal cell and metastatic carcinoma marker." (PMID 34019593, 2021). "CD44 is a major marker for stem-like cancer cells and is highly expressed in metastatic cancer cells." (PMID 27650542, 2016). "In particular, the cell surface protein CD44 is a major marker for stem-like cancer cells and is also expressed in metastatic cancer cells." (PMID 24498388, 2014). "Previous studies have indicated that CD44 overexpression and activation plays a role in the trafficking of metastatic cancer to distant sites." (PMID 22168923, 2011). "More importantly, the expression of Oct4, Sox2, Gli1, CD44, CD133, p-AKT, and p-ERK was significantly higher in metastatic cancer tissues than in primary cancer tissues." (PMID 26769843, 2016). "Furthermore, a positive correlation of the gene expression from two different metastatic cancer data suggesting the involvement of KDM6B in regulating HIF1α, SOX2, and CD44 further indicates the stemness regulatory function of KDM6B in various cancer types." (PMID 35186918, 2022). "For instance, HGF and TGFβ are major regulators of EMT, and these also provide strong stimuli of GBM invasion and, upregulation of MET and CD44 activities, as well as an activated NFκB signaling pathway, was reported in both mesenchymal GBM and metastatic cancer." (PMID 31009513, 2019). "Given that uPA and CD44 colocalise with MDR1-positive cells in EOC samples, it could be a useful therapeutic target for therapy in this disease to overcome drug resistance in the late stage of metastatic cancer." (PMID 19603017, 2009).
Alzheimer disease (17 papers, 2005 to 2026). A progressive, neurodegenerative disease characterized by loss of function and death of nerve cells in several areas of the brain leading to loss of cognitive function such as memory and language. "CD44 expression is elevated in multiple types of CNS insults including ischemia, traumatic injury, Alzheimer’s disease (including multiple splice variants of CD44), Parkinson’s disease, and white matter diseases such as MS and animal models of MS." (PMID 32825309, 2020). "Data from Alzheimer’s disease patients has also revealed increases in other CD44 splice variants, in particular CD44v3 and CD44v10." (PMID 31551718, 2019). "Furthermore, CD44 has been implicated in the pathogenesis of Alzheimer’s disease through its involvement in immune system regulation." (PMID 38809924, 2024). "For instance, an increased expression of CD44 has been found in the blood and brain of patients with Alzheimer’s disease (AD), and a role of CD44 in amyloid β (Aβ) plaque formation has been reported." (PMID 40943148, 2025). "This protein can bind to fibrinogen, fibronectin, laminin, type V collagen, and integrins alpha-V/beta-1, hsa-miR-132-3p, and hsa-miR-212-3p, inversely related to CD44, which was previously found upregulated in severe Alzheimer’s disease." (PMID 35011725, 2022). "The pattern and morphology of the pan-CD44 labeling in prion-infected brain indicated an astrocytic source, as observed previously in Alzheimer’s disease." (PMID 31551718, 2019). "Similarly, expression of CD44 is significantly elevated in post-mortem Alzheimer’s disease brain when compared to age-matched control tissue." (PMID 41282250, 2025). "This aligns with a report in Nature Medicine suggesting that CD44 could serve as a cerebrospinal fluid (CSF) biomarker for Alzheimer’s disease (AD)." (PMID 40867844, 2025). "Consistent with our results, findings have suggested that IGF1, FLT1, and CD44 may be involved in the development and progression of Alzheimer’s disease and MetS." (PMID 38809924, 2024). "Enrichment analysis by the DAVID dataset was employed and highlighted the SPP1 as a novel target, with its receptor CD44 playing a significant role in the inflammatory cascade and disruption of insulin signaling, contributing to the neurodegenerative aspects of Alzheimer’s disease." (PMID 38809924, 2024). "Serpina3n (a mouse homologue of α1-antichimotrypsin), Cd44, and Ch25h expression levels were also verified, because of the novelty of the gene array results and their possible involvement in the physiopathology of Alzheimer's disease." (PMID 17375196, 2007). "SPP1, CD44, IGF1, and FLT1 were identified as crucial molecules in the main cluster of Alzheimer’s disease and metabolic syndrome." (PMID 38809924, 2024). "In AlzData database, the levels of CD44, CD93, and CD163 in patients with Alzheimer’s disease (AD) were significantly increased than those in normal controls." (PMID 35356296, 2022). "Likewise, proteomic mapping via MIBI of Alzheimer's disease (AD) human brain tissue has revealed microglial, dynamic subpopulations like CD33/CD44 high and HLA‐DR/P2RY12/ApoE low expressing cells." (PMID 41431371, 2025).
autoimmune disease (17 papers, 2012 to 2025). A disorder resulting from loss of function or tissue destruction of an organ or multiple organs, arising from humoral or cellular immune responses of the individual to their own tissue constituents. "Inflammation that involves CD44 comprises in parts CD44–HA interactions that alternate cell functionalities at the site of lesion or injury and has been implicated in autoimmune diseases and cancers." (PMID 36100762, 2023). "Clinically, CD44 expression and isoform profiles serve as prognostic and predictive biomarkers and represent potential therapeutic targets in both oncology and autoimmune disorders." (PMID 41009438, 2025). "CD44 levels were reported to be higher in numerous malignancies, chronic inflammatory diseases, and autoimmune disorders." (PMID 35200757, 2022). "There is increasing evidence to suggest that CD44 plays a pivotal role in autoimmune diseases and its expression is increased in synovial cells in patients with rheumatoid arthritis, which correlates with synovial inflammation." (PMID 22900150, 2012). "Moreover, osteopontin and its receptor CD44 are also elevated in other autoimmune disorders, such as experimental colitis, an animal model of human inflammatory bowel disease." (PMID 37810891, 2023). "Antibodies to CD44 have been used to successfully ameliorate murine models of autoimmune disease." (PMID 23785450, 2013). "As a proinflammatory mediator secreted by numerous immune cells, MIF promotes inflammation and autoimmune diseases mainly by binding with the receptor CD74 and co-receptor CD44, CXCR4, or CXCR2." (PMID 36046240, 2022). "Effector T cells (CD62L-CD44+) and naïve T cells (CD62L+CD44-) along with CD25 collectively represent the activation level of CD4+ T cells in EAU and various autoimmune diseases." (PMID 34093583, 2021). "T cells from these mice show an increase in the expression of the activation marker CD44, but the mice do not show any sign of inflammation or autoimmune disease." (PMID 33133093, 2020). "The interaction of CD44 with HA has been shown to enhance various cellular functions such as cell proliferation and migration, and activation of PKC, PI3K and MAPK-signaling pathways which have all been shown to induce inflammatory processes in autoimmune diseases including lupus nephritis." (PMID 22900150, 2012).